CFTR (CF transmembrane conductance regulator)
Diseases named in the same sentence as CFTR in open-access papers (continued):
Sharing a sentence is not in itself a finding about the gene and the disease.
cystic fibrosis (continued). "Cystic fibrosis is a life-shortening, genetic multi-system organ disease that affects 100.000 people worldwide and whose clinical manifestations are due to mutations in the cystic fibrosis transmembrane conductance regulator (CFTR)." (PMID 39339703, 2024). "Cystic fibrosis, a recessive disorder arising from diverse mutations in the cystic fibrosis transmembrane conductance regulator (CFTR) gene, affects individuals with mutations unresponsive to CFTR modulators, leaving approximately 8% of patients without effective treatments." (PMID 39726634, 2024). "CAs of the CFTR gene complicate the cystic fibrosis diagnosis process, classification of pathogenic variants, and determination of the clinical picture of the disease and increase the need for additional studies to determine their pathogenicity and modulatory effect in response to targeted therapy." (PMID 38392563, 2024). "Cystic fibrosis is the most common life-limiting hereditary disease in the Caucasian population, caused by dysfunction of the CF Transmembrane Conductance Regulator (CFTR), an anion channel lining the epithelial cells throughout the body." (PMID 38541878, 2024). "In addition, hiBCs derived from healthy donors (hiPSC No4) express CFTR, which makes it possible to analyze changes in protein localization when genetically editing cystic fibrosis mutations in hiBCs." (PMID 38737127, 2024). "Cystic fibrosis is primarily caused by CFTR defects and affects multiple vital organs." (PMID 39126669, 2024). "Cystic fibrosis is an autosomal recessive genetic variation, resulting from over 700 CF-causing mutations of the cystic fibrosis transmembrane regulator (CFTR) gene, with the mutation of phenylalanine 508 accounting for up to 90% of all CFTR cases." (PMID 39599743, 2024). "In 2022, the European Cystic Fibrosis Society updated the diagnostic criteria for CFTR-RD." (PMID 39062716, 2024). "Cystic fibrosis is a monogenic disease caused by mutations in the CFTR gene that causes the lungs and other organs to produce thick mucus that blocks the airways of the lungs and makes breathing difficult, leading to lung damage, respiratory failure and chronic lung infections." (PMID 39543114, 2024). "CFTR is the same gene that is mutated in cystic fibrosis and is under the control of secretin." (PMID 38409681, 2024). "However, apart from this variant, carriers of single cystic fibrosis-causing variants of the CFTR gene were previously also shown to be more susceptible to the severe form of COVID-19." (PMID 39062917, 2024). "As a positive control, we tested whether we see the expected number of children harbouring homozygous disease-causing variants in CFTR, the causative gene for Cystic Fibrosis." (PMID 39839975, 2024). "Cystic fibrosis is an autosomal recessive disease caused by a mutation in the gene encoding the cystic fibrosis transmembrane conductance regulator (CFTR) anion channel, which is responsible for maintaining water and ion balance intra- and extracellularly (Ikpa, Bijvelds, and de Jonge 2014)." (PMID 38081555, 2024). "Silent variants in CFTR and F9 may decrease protein abundance through alterations to translation elongation, leading to cystic fibrosis and Hemophilia B, respectively." (PMID 38355921, 2024). "Cystic fibrosis met our selection criteria of having a causative gene (CFTR) with known treatments and is well-suited for validation purposes as we can verify whether the gene and treatment links are extracted by our pipeline." (PMID 38977662, 2024). "Four of these decedents had compound heterozygous P/LP/VUS variants in genes associated with recessive disorders, including CFTR (cystic fibrosis), BCKDHA (maple syrup urine disease), MPDZ (congenital hydrocephalus-2), and GDAP1 (Charcot-Marie-Tooth disease, type 4A)." (PMID 38229148, 2024).
cystic fibrosis (continued). "Finally, the influenceof CFTR mutations on baseline airway surface liquid pH was exploredby using SERS-MS to measure the pH in ALIs grown from Cystic Fibrosisand non-Cystic Fibrosis donors." (PMID 38659220, 2024). "As a second example, consider the F508del allele of CFTR (cystic fibrosis transmembrane conductance regulator) which when heterozygous promotes resistance to cholera infection but when homozygous causes cystic fibrosis." (PMID 39374830, 2024). "Cystic fibrosis, the most common inherited disease affecting respiratory cilia, is caused by mutations in the CFTR gene, leading to impaired electrolyte balance and severe respiratory complications, including mucociliary dysfunction and eventually respiratory failure." (PMID 39408877, 2024). "To study the ability of antisense oligonucleotides to induce readthrough of premature stop codons, we first developed a reporter mRNA in which translation of nanoluciferase requires the readthrough of the CFTR G542X mutation, the most frequent nonsense mutation in cystic fibrosis patients." (PMID 39011883, 2024). "The pluripotency and genomic profile of the iPSC cell lines have been validated as a resource that can be used for pharmacological investigations and drug screening associated with mutations of CFTR genes and provide hope for curing cystic fibrosis in the future." (PMID 37274156, 2023). "Cystic fibrosis is an autosomal recessive genetic disease characterized by chronic obstructive lung disease and caused by mutations in the CF transmembrane conductance regulator (CFTR) gene." (PMID 37111072, 2023). "Indeed, inflation of organoids has been used to predict patient response to drugs in cystic fibrosis, which is caused by loss-of-function mutations in CFTR." (PMID 37643009, 2023). "Cystic fibrosis is the most common, severe, autosomal recessive disease in the Caucasian population and is caused by mutations in the CF transmembrane conductance regulator (CFTR) gene." (PMID 37967223, 2023). "Lumacaftor/ivacaftor and elexacaftor/tezacaftor/ivacaftor are approved in the United States for the treatment of cystic fibrosis in those with homozygous or compound heterozygous F508del cystic fibrosis transmembrane conductance regulator (CFTR) mutations, respectively." (PMID 36662672, 2023). "The first molecule prevented the degradation of a mutated form of CFTR (ΔF508-CFTR), a common cystic fibrosis mutation, which is unstable and therefore, leads to rapid polyubiquitination and degradation of the protein, causing the phenotype observed in this disease." (PMID 37896202, 2023). "Loss of CFTR protein might cause different clinical phenotypes in patients, including cystic fibrosis, diffuse bronchiectasis, acute or recurrent pancreatitis and CAVD." (PMID 36604502, 2023). "Cystic fibrosis is a life-shortening autosomal recessive trait of exocrine glands and CFTR-expressing epithelia that is caused by mutations in the Cystic Fibrosis Transmembrane Conductance Regulator (CFTR) gene." (PMID 36778025, 2023). "Over the last fifteen years, with the approval of the first molecular treatments, a breakthrough era has begun for patients with cystic fibrosis, the rare genetic disease caused by mutations in the gene encoding the cystic fibrosis transmembrane conductance regulator (CFTR)." (PMID 37445715, 2023). "Cystic fibrosis, an autosomal recessive disorder caused by mutations in the cystic fibrosis transmembrane conductance regulator (CFTR) gene that codes for the CFTR chloride channel, is one of the most common life-shortening hereditary diseases affecting the lungs and other organs." (PMID 37175488, 2023). "A near-exonic CFTR variant was detected in a fourth patient (P7) with cystic fibrosis." (PMID 37558402, 2023). "The F508del mutation is one of the most common in the CFTR gene that causes cystic fibrosis." (PMID 36831203, 2023).
cystic fibrosis (continued). "Indeed, the functionality of the CFTR protein (mutated in cystic fibrosis patients) has been assessed in primary cystic fibrosis intestinal organoids." (PMID 36959902, 2023). "Furthermore, 28 improved CFTR-dependent transepithelial conductance in primary cells from a cystic fibrosis patient bearing the ΔF508-CFTR mutation, suggesting that levels of functional CFTR were enhanced at the cell surface, too." (PMID 36677746, 2023). "Cystic fibrosis is an autosomal recessive disease that results from inheriting two copies of a pathogenic mutation in the cystic fibrosis transmembrane conductance regulator (CFTR) gene, one from each parent." (PMID 37511977, 2023). "Also it displayed decreased NO in the exhalation of patients with cystic fibrosis due to the thick and sticky mucus, high volume of airway secretions, sinus involvement and obstruction of their outlet ducts and underlying CFTR dysfunction." (PMID 38053097, 2023). "Mutations or polymorphisms in CFTR gene result in cystic fibrosis, an autosomal recessive disease." (PMID 36983403, 2023). "We are currently witnessing transformative change for people with cystic fibrosis with the introduction of small molecule, mutation-specific drugs capable of restoring function of the defective protein, cystic fibrosis transmembrane conductance regulator (CFTR)." (PMID 36755044, 2023). "Loss-of-function mutations in the gene encoding CFTR result in the lethal disease cystic fibrosis." (PMID 36694009, 2023). "Cystic fibrosis is the most common autosomal recessive disease among Caucasians, affecting approximately 1 in 2500–4000 newborns, and is caused by loss of function mutations in the gene encoding the CFTR protein." (PMID 37315117, 2023). "Reduced Wnt/β-catenin signaling in F508del-CFTR osteoblasts was corrected via genetic or pharmacologic targeting of Keratin 8, reinforcing that cystic fibrosis severity and associated comorbidities depend on the presence of different modifier genes and complex alleles." (PMID 36979360, 2023). "Therefore, the aim of the present study was a comparative analysis of common pathogenic CFTR gene variants and genotypes in Russian men with cystic fibrosis and Russian patients with CBAVD syndrome." (PMID 38003474, 2023). "Cell-based NIPT gave an accurate result in two cases at risk of autosomal recessive disorders, where the parents carried either different diastrophic dysplasia causing variants in the SLC26A2 gene or the same cystic fibrosis disease-causing variant in the CFTR gene." (PMID 37829280, 2023). "The authors suggested that cystic fibrosis may result in specific immune defects due to a defective cystic fibrosis transmembrane conductance regulator (CFTR) on the cell membrane, leading to increased titer loss over time and impaired vaccine response." (PMID 37896898, 2023). "S737F is a Cystic Fibrosis transmembrane conductance regulator (CFTR) missense variant." (PMID 37047546, 2023). "Lumacaftor (Vx-809) is a common corrector used in cystic fibrosis treatment which enhances the folding of mutated F508del-CFTR, one of the most prevalent impaired proteins underlying the disease, promoting a higher localization of the mutant protein on the cell membrane." (PMID 36835664, 2023). "Cystic fibrosis is an autosomal-recessive disorder induced by loss-of-function mutations in the gene encoding for cystic fibrosis transmembrane conductance regulator (CFTR) protein." (PMID 37461324, 2023). "Cystic fibrosis is a monogenic disease caused by mutations in the CF transmembrane conductance regulator (CFTR) gene that may impair expression, function or stability of the CFTR protein." (PMID 37325471, 2023). "Cystic fibrosis is a genetic disorder that arises due to mutations in the CF transmembrane conductance regulator (CFTR) gene, a chloride and bicarbonate ion transport channel that contributes to the absorption and secretion of ions across epithelial surfaces in the body." (PMID 36824474, 2023).
cystic fibrosis (continued). "Thus, it would be reasonable to propose that L927P causes cystic fibrosis by altering the flexibility of the transmembrane hinge in NBD-dimerized CFTR conformations." (PMID 36949202, 2023). "Similarly, poly-SUMO2/3 modification of mutant CFTR protein associated with cystic fibrosis promotes its degradation, whereas SUMO1 conjugation enhances CFTR stability." (PMID 38201212, 2023). "The available data suggest that abnormal CFTR function causes an intrinsic defect in osteoblastogenesis, hampering new bone formation and the failure to reach an optimal bone mass peak and reduced bone turnover in cystic fibrosis patients." (PMID 36979360, 2023). "Cystic fibrosis is an autosomal recessive disorder caused by mutations in the gene for the cystic fibrosis transmembrane conductance regulator (CFTR) protein, an anion-conducting transmembrane channel that regulates electrolyte transport and mucociliary clearance in the airways." (PMID 36232826, 2022). "On the contrary, activations of the UPS process could be employed as a therapeutic measure in some diseases, such as for FGF2 in AD and PD, IDE in AD, trafficking-deficient CFTR in cystic fibrosis, and trafficking-deficient pendrin in Pendred syndrome." (PMID 35774225, 2022). "The aim of this study was to test the hypothesis that treatment with CFTR modulators is associated with an improvement in the key direct determinants of glucose regulation in children and young adults affected by Cystic Fibrosis." (PMID 35887914, 2022). "Cystic fibrosis, the most common monogenic life-threatening disease, is caused by mutations of the cystic fibrosis transmembrane conductance regulator (CFTR) gene, which encodes for a chloride channel located at the apical membrane of respiratory epithelial cells." (PMID 36012204, 2022). "Cystic fibrosis, the most common lethal autosomal recessive genetic disease in the Caucasian population, results from pathogenic variants in the CF transmembrane conductance regulator (CFTR) gene." (PMID 35372502, 2022). "Thus, for example, CFTR p.Phe508del, the classical cystic fibrosis-causing variant, had an OR of only 2.5 (95% CI 1.7–3.9) for CP." (PMID 35974416, 2022). "Moreover, patients with cystic fibrosis—a genetic disease caused by CFTR gene mutation—have dysregulation of calcium homeostasis including impaired calcium absorption and excretion, as well as low bone mineral density." (PMID 36399482, 2022). "However, InDels on loops can still have structural or functional effects—for example, the F508del of the cystic fibrosis transmembrane conductance regulator (CFTR) is one of the most common mutations that causes cystic fibrosis." (PMID 36291643, 2022). "Indeed, males with cystic fibrosis caused by mutations in CFTR have exhibited a wide range of testicular histology, from normal to severely pathological." (PMID 35725394, 2022). "Cystic fibrosis is a rare genetic multisystemic disease, the manifestations of which are due to mutations in the gene encoding the CF transmembrane conductance regulator (CFTR) protein and can lead to respiratory insufficiency and premature death." (PMID 35681464, 2022). "Cystic Fibrosis is a monogenic disease caused by pathogenic mutations in the Cystic Fibrosis Transmembrane conductance Regulator (CFTR) gene which encodes the CFTR protein, an anion channel responsible for chloride and bicarbonate ion transport across epithelial cells." (PMID 35721541, 2022). "Cystic fibrosis is a monogenic epithelial disease caused by mutations in the CFTR gene." (PMID 35922154, 2022). "Cystic fibrosis is a common autosomal recessive disorder, caused by cystic fibrosis transmembrane conductance regulator (CFTR) gene mutations, with highest prevalence in Europe, North America and Australia, affecting about 1 in 2000–3000 Caucasian population newborns." (PMID 35757498, 2022).
cystic fibrosis (continued). "The hypogonadotropic manifestations of cystic fibrosis may be partly explained by abnormal neuropeptide-vesicle trafficking, due to CFTR mutations." (PMID 35725394, 2022). "Cystic fibrosis is a life-threatening genetic disease affecting the respiratory and digestive systems that is caused by mutations to the CF transmembrane conductance regulator (CFTR) anion channel." (PMID 36425670, 2022). "Cystic fibrosis is an autosomal recessive disease caused by mutations in the cystic fibrosis transmembrane conductance regulator (CFTR) gene affecting the functional expression of the CFTR protein, an ion channel that regulates the transport of chloride and bicarbonate at the cell surface." (PMID 35525974, 2022). "Furthermore, European populations harbour the highest frequencies of CFTR trafficking mutations, suggesting that the rate of cystic fibrosis patients responding to CFTR correctors is overall higher in Europe compared to other populations." (PMID 34652573, 2022). "CFTR mutations can lead to the development of cystic fibrosis." (PMID 35995803, 2022). "Cystic fibrosis is a multisystem disease caused by mutations in a single gene located on human chromosome 7 that encodes the cystic fibrosis transmembrane conductance regulator (CFTR) protein − an epithelial chloride channel with wide tissue expression." (PMID 36313742, 2022). "Cystic fibrosis, the most common autosomal recessive disorder in Caucasians, is caused by mutations in the cystic fibrosis transmembrane conductance regulator (CFTR) gene, which encodes a cAMP-activated chloride and bicarbonate channel that regulates ion and water transport in secretory epithelia." (PMID 35707985, 2022). "Cystic fibrosis is associated with the misfolding and premature degradation of the cystic fibrosis transmembrane conductance regulator (CFTR) mutant CFTRΔF508, it has been demonstrated that RNF5 targeted CFTRΔF508 for degradation through the endoplasmic reticulum-associated degradation (ERAD)." (PMID 36270989, 2022). "Impaired activity of the chloride channel CFTR is the cause of cystic fibrosis." (PMID 35739107, 2022). "Indeed, a recent landmark study shows that cystic fibrosis patients with mutations that impact CFTR production, trafficking, and/or gating defects score lower on cognitive assessments and display subtle brain tissue alterations." (PMID 36462404, 2022). "A particular type is the CFTR (cystic fibrosis transmembrane conductance regulator), epithelial chloride channel regulating secretion and water balance in multiple organs, and whose loss of function mutations underlie cystic fibrosis pathologies." (PMID 36580479, 2022). "Recently, we proposed a pharmacological approach based on the use of CFTR correctors, specifically developed for rescuing type II mutations of the Cystic Fibrosis Transmembrane Regulator (CFTR) (e.g., F508del-CFTR), causing cystic fibrosis." (PMID 36293223, 2022). "Cystic fibrosis is a hereditary disease mainly caused by the deletion of the Phe 508 (F508del) of the cystic fibrosis transmembrane conductance regulator (CFTR) protein that is thus withheld in the endoplasmic reticulum and rapidly degraded by the ubiquitin/proteasome system." (PMID 36293130, 2022). "The multi-organ disease cystic fibrosis is caused by mutations in the gene encoding the CF transmembrane conductance regulator (CFTR) protein, a cAMP regulated chloride (Cl−) and bicarbonate (HCO3−) ion channel expressed at the apical plasma membrane (PM) of epithelial cells." (PMID 35269829, 2022). "Phenotypes and CFTR variants in 37 patients with cystic fibrosis." (PMID 36369753, 2022). "Approximately 10% of cystic fibrosis patients harbor nonsense mutations in the cystic fibrosis transmembrane conductance regulator (CFTR) gene which can generate nonsense codons in the CFTR mRNA and subsequently activate the nonsense-mediated decay (NMD) pathway resulting in rapid mRNA degradation." (PMID 35487895, 2022).